TNF (tumor necrosis factor)
Diseases named in the same sentence as TNF in open-access papers (continued):
Sharing a sentence is not in itself a finding about the gene and the disease.
Arthritis (continued). "Given the dual biological functions of TNF-α in arthritis mediated by TNFRI and TNFRII, and potential technical difficulties depleting EV-carried TNF-α in vivo, neutralizing TNF-α with biologics may not be an ideal therapeutic approach for treating OA." (PMID 34691080, 2021). "Interestingly, TNF levels in the heart remained increased, even after overt signs of arthritis had diminished." (PMID 33924323, 2021). "We also found that the resolving phenotype correlated with more dynamic mitochondrial morphology in response to TNFα, manifesting as increased connectivity (linear pixels in green) in resolving arthritis FLS compared to veRA, which displayed a more punctate/fragmented (in purple) morphology." (PMID 34512657, 2021). "In addition, osteoclast-deficient mice showed protection from bone erosion when crossed with tumor necrosis factor-α (TNF-α)-expressing transgenic mice, which spontaneously develop arthritis." (PMID 34638736, 2021). "However, the anti-TNF treatment showed reduced efficacy and limited bone protection in advanced arthritis." (PMID 33846342, 2021). "Interestingly, GA treatment attenuated the severity of arthritis in mice with collagen-induced arthritis and human TNF-α transgenic mice." (PMID 32938830, 2020). "A variety of mouse models of human RA is established such as CIA, CAIA, tumor necrosis factor-transgenic mice, streptococcal cell wall-induced arthritis, proteoglycan-induced arthritis, and K/BxN-transgenic nice with specific features are available to investigate unique arthritic conditions." (PMID 32165681, 2020). "Similarly, mouse models overexpressing human TNF have been shown to develop spontaneous arthritis also missing however evidence of new bone formation, which is the main feature of SpA." (PMID 33023659, 2020). "Interestingly, ATB-346, a novel H2S-releasing naproxen, more efficiently reduces TNF-α release in a rat model of arthritis, and GYY-4137 inhibits the expression of effectors of the TNF pathway." (PMID 33050005, 2020). "Intracellular cytokine staining of splenocytes showed that, in addition to Th17 cells, lack of SR-A also dramatically reduced the frequency of Th1 cells, i.e., TNF-α-producing CD4+ T cells, underscoring an important role of SR-A in arthritis-associated inflammation." (PMID 32312978, 2020). "Thus, an in vivo study showed that p-coumaric acid was efficient against the expression of tumor necrosis factor (TNF-α) involved in arthritis." (PMID 32756379, 2020). "Therefore, human chondrocytes (HC) were abstracted and cultured from human cartilage samples and IL-1β, LPS or TNF-α were added to simulate the microenvironment of joint inflammation in vivo." (PMID 32802182, 2020). "When HLA-DQ8 mice treated with P. histicola, which is isolated from human duodenum, it showed a significantdecrease of arthritis as a result of suppressing the serum level of various proinflammatory cytokines like IL-2, IL-7, and also the TNF-α (Tumor necrosis α)." (PMID 32405173, 2020). "Interestingly, in a TNF-induced model of citrullination and arthritis, protein citrullination is executed by PAD2 instead of PAD4." (PMID 33584645, 2020). "Furthermore, ursolic acid reduced the incidence and severity of CIA-induced arthritis, accompanied by the decreased expression of TNF-α, IL-1β, IL-6, IL-21, and IL-17 in arthritic joints." (PMID 32116720, 2020). "Mouse models helped identify the participation of inflammatory cells such as macrophages in developing arthritis and myositis and to establish the damage, and the role of pro-inflammatory factors such as tumor necrosis factor (TNF)-α, MCP-1, and interferon (IFN)-γ." (PMID 32516914, 2020). "They observed that PTEN deficiency increased the osteoclast development in vivo and in vitro by enhancing the expression of the RANKL‐induced osteoclast transcription factor, and in a human TNF‐transgenic arthritis model, there was increased local osteoclast activity in the joints." (PMID 32485091, 2020).
Arthritis (continued). "Therefore, data from this study demonstrate the ability of FLS activated by TNF-α to promote neuronal sensitization, results that highlight the importance of both nonneuronal and neuronal cells to the development of pain in arthritis." (PMID 32332252, 2020). "HMGB1 can induce the release of tumor necrosis factor-α (TNF-α), interleukin-1β (IL-1β), interleukin 1 (IL-1) and interleukin 6 (IL-6) and it controls the initiation and development of inflammation in various experimental arthritis models." (PMID 32709223, 2020). "Together with other cytokines such as IL17, both IL6 and TNF are known to induce the RANKL expression that subsequently enhances osteoclastogenesis and bone destruction, and are thus considered pathogenic in S. aureus arthritis." (PMID 32111171, 2020). "It was reported to be effective in lowering TNF-α and other indices of arthritis in mice." (PMID 33379296, 2020). "In this study, we found that a traditional Chinese decoction, Juanbi-Tang (JBT), JBT attenuated the symptoms of collagen-induced arthritis (CIA) mice and in tumor necrosis factor transgenic (TNF-Tg) mice by attenuating the arthritis index and hind paw thickness." (PMID 32116720, 2020). "Moreover, it has been found that vitamin D inhibits the synthesis of several cytokines, including tumor necrosis factor alpha (TNF-α) which has a key role in joint inflammation and in extra-articular involvement in rheumatic conditions." (PMID 32414130, 2020). "Radiographic axial spondyloarthritis (r-axSpA) is a chronic inflammatory form of arthritis in which tumor necrosis factor (TNF)-α, a potent inducer of inflammatory response and a key regulator of innate immunity and of Th1 immune responses, plays a central role." (PMID 32303225, 2020). "Interestingly, hippocampal immune response in these models indicates a different regional pattern of neuroinflammation compared to myeloid cell-based, TNF-driven arthritis." (PMID 33362800, 2020). "While in hTNFtg mice, reactive astrogliosis was concluded by increased Gfap staining intensity in the cortex, arthritis driven by overexpression of murine TNF was associated with activation of microglia, but not astrocytes." (PMID 33362800, 2020). "PAD2 mediated TNFα-induced citrullination and arthritis but was dispensable for NET formation." (PMID 33584645, 2020). "Administration of GA attenuates the severity of arthritis in human TNF-α transgenic mice." (PMID 32938830, 2020). "The treatment for arthritis with anti-TNF-α results in increased susceptibility to VL, suggesting that TNF-α could act as a primary effector component." (PMID 31024534, 2019). "TNF-α has also been reported as accelerating arthritis signals when injected into animals." (PMID 31683648, 2019). "Similarly, IRF1 was highly expressed in the inflamed synovium in human TNF transgenic (hTNFtg) mice that constitutively overexpress human TNF, and consequently develop spontaneous arthritis." (PMID 31285419, 2019). "TNF-blockade is an effective treatment with well-documented anti-inflammatory effects for several chronic inflammatory diseases, including different types of arthritis." (PMID 30770760, 2019). "Previous studies showed increase in arthritis severity when TNF-α works in synergy with IL-1β." (PMID 30691120, 2019). "Application of sCD83 not only reduced the clinical symptoms of arthritis, but also inhibited the antigen-specific T cell proliferation upon mBSA-restimulation and impaired production of key inflammatory effectors, including IL-17A, TNFα, IFNγ, and IL-6." (PMID 31001257, 2019). "Simultaneous overexpression of RANKL and TNF in Tg197/TgRANKL mice resulted in an aggressive arthritic phenotype, characterized by earlier arthritis onset and exacerbated clinical symptoms, such as reduced body weight gain and increased arthritis scores compared to Tg197 arthritic control mice." (PMID 30804932, 2019).
Arthritis (continued). "The results indicate that SHW could be used to improving arthritis by reducing inflammatory factors (IL-6 and TNF-alpha)." (PMID 30606189, 2019). "Similarly, in the murine model of enthesitis and arthritis dependent on stromal cell overexpression of TNF (TNF(ΔARE)), hind limb unloading of mice significantly suppressed inflammation of the Achilles tendon, as well as further ossification." (PMID 31722720, 2019). "PlGF-2123-144-α-TNF even at 0.1 μg completely suppressed the arthritis score at the treated paw, and joint histology in the treated paw appeared normal, whereas synovial proliferation, leukocyte infiltration, and cartilage degeneration were observed in untreated control joint." (PMID 31870429, 2019). "Furthermore, in Freund's adjuvant-induced arthritis, rheumatoid markers, TNF-α, IL-10, p38 MAPK, and antioxidant parameters were measured." (PMID 31736366, 2019). "Our study design limited the breadth of our conclusions because we utilized a pan genetic ablation of iNOS and a cell-targeted approach may have elucidated specific cellular effects of iNOS on TNF-induced arthritis." (PMID 31727153, 2019). "In one study, cFos-deficient mice with no osteoclasts were mated with TNF-α transgenic mice—model mice for arthritis—and despite the onset of arthritis, bone destruction was notably regulated." (PMID 31382539, 2019). "In osteochondral destruction in arthritis, various immune cells and osseous tissues interact closely via mediators, such as tumor necrosis factor (TNF) α, interleukins (ILs), matrix metalloproteinase (MMP), and a disintegrin and metalloproteinase with thrombospondin motifs (ADAMTS)." (PMID 31382539, 2019). "An early intensive treatment including TNF inhibitors may be necessary to control cumulative inflammatory cytokines resulting from the complication of gout and other arthritis." (PMID 31577714, 2019). "This might on the one hand reflect that patients with arthritis/arthralgia are suffering from a more severe disease and therefore need more frequently anti-TNF treatment." (PMID 31039159, 2019). "The differential effects of Sh3bp2 gain-of-function mutation between arthritis and lupus models might be attributed to the distinct pathological impact of TNF under arthritis and lupus conditions." (PMID 31052273, 2019). "For over twenty years it has been known that tumor necrosis factor (TNF), which is an inflammatory cytokine, plays a major role in arthritis and that targeting TNF (for example with a monoclonal antibody such as infliximab) is effective and improved the symptoms of fatigue." (PMID 31554244, 2019). "As Lpps induced TNF-α release by macrophages and anti-TNF treatment attenuated the severity of Lpp-induced arthritis, we posed the question of whether the bacterial eliminating effect of Lpp was TNF-dependent." (PMID 31226163, 2019). "However, given its potential to alter LV disfunction in RA, we investigated the role of genetic iNOS ablation on draining LNs, LV contraction, and arthritis in TNF-Tg mice with inflammatory-erosive arthritis." (PMID 31727153, 2019). "Our results demonstrated that abundance of RANKL accelerated TNF-driven arthritis onset and disease severity characterized by massive osteoclastogenesis and bone resorption, aggressive pannus expansion and immense infiltration of inflammatory cells mainly of myeloid origin." (PMID 30804932, 2019). "In particular, anti-TNF treatment, onset of further EIM and IBD-related surgery which are all indicative of a severe course of disease, are risk factors for the presence of arthritis/arthralgia, but also with sacroiliitis/ankylosing spondylitis in IBD patients." (PMID 31039159, 2019). "Our findings stress that also intrathecal inflammatory pathways are related to arthritis symptoms and may be affected by TNF blockade." (PMID 30770760, 2019). "TNF is a crucial cytokine for the development of articular pain during arthritis." (PMID 32038637, 2019).
Arthritis (continued). "However, little else is known about the effects of TNF blockade in the human intrathecal compartment or the relationship between CSF effects, CNS-related arthritis symptoms and peripheral inflammation." (PMID 30770760, 2019). "Furthermore, a previous study showed that the blockade of TNF, but not IL-1, resulted in a reduction of bone erosions in a murine TNF-driven arthritis model." (PMID 31226163, 2019). "Arthritis in TNF-α transgenic mice was not affected by IL-6 deficiency, while CIA was abolished, possibly involving inhibition of Treg differentiation by this cytokine in the latter model." (PMID 30937315, 2019). "Third, evaluation of TNF-α as an inflammatory cytokine, in the synovium of arthritis joint." (PMID 31324245, 2019). "Importantly, all of these studies were performed in male mice, but when we investigated female mice, we found significantly altered progression indicating that in the TNF-Tg mouse model, these lymphatic and arthritis phenotypes are sexually dimorphic." (PMID 31727153, 2019). "Therefore, in this work we aimed to investigate the role of TNF expressed in the DRG in driving persistent joint nociception even during the resolving phase of joint inflammation in an experimental model of arthritis in mice." (PMID 32038637, 2019). "This suggests a possible role for CNS inflammation in arthritis that may be affected by TNF blockade." (PMID 30770760, 2019). "Studies have shown that CHIKV induces different inflammatory cytokines/chemokines (TNF, IL-1β, IL-6, IFN-γ, IL-8, and MCP-1), which might be associated with arthritis like pathogenesis during CHIKV infection." (PMID 31031770, 2019). "In contrast, TNF-driven arthritis was severely aggravated in TNFR2 KO mice." (PMID 29751683, 2018). "Osteoarthritis (OA), an inflammatory form of arthritis, is characterized by synovial inflammation and cartilage destruction largely influenced by two key proinflammatory cytokines—interleukin-6 (IL-6) and tumor necrosis factor α (TNF-α)." (PMID 29316707, 2018). "The level of TNF- α was up-regulated in the arthritis patient." (PMID 30618728, 2018). "Potentiation of Fas-induced apoptosis by CRABP2 silencing could be of clinical interest because it persisted in the presence of TNFα and IL1β, two pro-inflammatory stimuli that are present in arthritis and that increase RA FLS survival." (PMID 29880835, 2018). "Interestingly, acetylation-dependent GR increases the transcription of SLPI, which suppresses inflammation and joint damage in arthritis by downregulating TNF-α." (PMID 30034392, 2018). "MAYV replication in macrophages induces tumor necrosis factor (TNF) synthesis in association with fever, since TNF promotes an inflammatory profile characteristic of arthritis." (PMID 30254258, 2018). "In the current study, we are surprised to find that the expression of SATB2, a critical transcriptional node for osteoblast differentiation, is negatively associated with the levels of TNF-α in OVX-induced bone loss and IL-1β induced arthritis mice by immunohistochemistry." (PMID 29435145, 2018). "Based on these results, we suspected that decreases in TNF-α and Cx43 may be involved in the control of arthritis by treadmill running." (PMID 29865282, 2018). "Signal blockade of IL-6 or TNFα markedly ameliorates arthritis in KO1 mice." (PMID 29422084, 2018). "Therefore, we cannot discuss how TNF-α and Cx43 are involved in the suppression of arthritis by treadmill running in CIA rats." (PMID 29865282, 2018). "It has been reported that thymoquinone reduces TNF-α and IL-6 in blood and arthritis tissues." (PMID 30049280, 2018). "In addition, the supernatants were collected from each group, and CBAs were used to evaluate the levels of pro-inflammatory factors (IL-17A, TNF-α and IL-6), which are closely related to arthritis progression." (PMID 29370826, 2018).
Arthritis (continued). "However, pretreatment with a TNF-α inhibitor worsened the outcome of S. aureus-induced arthritis compared to controls, with a 30-fold increase in bacterial load in the kidneys and a more pronounced weight loss." (PMID 29440371, 2018). "Here, we determined that treatment with an AMPK agonist reduced the inflammatory response in hypoxia- or TNF-α-induced RA FLSs and ameliorated the severity of arthritis in rats with CIA, suggesting that AMPK is also a viable novel target for the treatment of RA." (PMID 30100905, 2018). "Most times the fusion of peptide and Fc reduced the efficacy of the active peptide in vivo; however, in our research, HM-3-Fc showed better efficacy than HM-3 in the improvement of arthritis index, TNF-α expression by macrophages and CD31 expression in the immunohistochemical analysis." (PMID 30201867, 2018). "In addition to TNFα and IL-1β, multiple reports have also shown that ROS are elevated in models of arthritis, which are known to be activators of TRPA1." (PMID 30326593, 2018). "Interestingly, a Tg197 transgenic human TNF mouse model for polyarthritis, confirmed in vivo the validity of properly designed NanobodyTM bivalent constructs against arthritis." (PMID 28824615, 2017). "Instead, arthritis could be induced in other mice by the adoptive transfer of fibroblast-like synoviocytes from TNF-α transgenic mice." (PMID 28753982, 2017). "In TNF-α transgenic mice, arthritis was completely inhibited by IL-1 deficiency, suggesting that IL-1 acts downstream of TNF-α, while IL-6 was not required for the development of arthritis in this animal model." (PMID 28753982, 2017). "The synoviocytes that overexpressed TNF-α acquired an aggressive phenotype, and exhibited increased proliferation and decreased adhesion to the extracellular matrix for mediating immunity-independent arthritis, which is driven by TNF-α." (PMID 28753982, 2017). "Therefore, the objective of our study was to evaluate the clinical and MRI outcome of cervical spine arthritis in a group of consecutive patients with JIA who received anti-TNFα treatment early in disease course." (PMID 28506237, 2017). "Patients with arthritis should be monitored for early signs of opportunistic infection and, if confirmed, it may be necessary to withdraw anti-TNF-α therapy until the infection is properly treated." (PMID 29065914, 2017). "Interestingly, platelets activated by pro-inflammatory cytokines (e.g., TNF-α, IL-6) play an important role in the pathogenesis of joint inflammation." (PMID 28247163, 2017). "On the other hand, IL-10 suppresses the production of TNF-α and progression of arthritis." (PMID 28555160, 2017). "Initial findings in a previous study showed that FTS treatment reduced the clinical arthritis score in the AIA model, and that this treatment was associated with reduced levels of various pro-inflammatory cytokines (IFN-γ, TNF-α, IL-6, and IL-17) in the serum at study end." (PMID 28736556, 2017). "Our findings also provide support for the proposition that arthritis could be driven/sustained by different inflammatory pathways in different patients resulting in a heterogeneous response to TNFα inhibitors." (PMID 28488248, 2017). "Supporting the anti-inflammatory role of PRL in arthritis, PRL-receptor-null mice exhibited increased joint swelling and higher joint expression of the genes encoding for TNFα, IL-1β, IL-6, IFNγ, IL-17A, IL-21, IL-22, IL-23, and IL-10 when subjected to monoarticular AIA (MAIA)." (PMID 28506283, 2017). "After validation of the model, we tested whether prophylactic and therapeutic TNF targeting affected spondylitis and arthritis." (PMID 28824645, 2017). "Suppressive activity of the extracts on fundamental molecules (TNF-α and T-cells) which play an essential role in the pathogenesis of arthritis observed in vitro could justify the net suppressive effect on inflammation and hyperalgesia." (PMID 28202019, 2017).